PCNA (proliferating cell nuclear antigen)
Diseases named in the same sentence as PCNA in open-access papers (continued):
Sharing a sentence is not in itself a finding about the gene and the disease.
tumor (continued). "LDHA, β-catenin, and PCNA increased in the tumour tissues induced by injection of APC-mutated CRC cells expressing control shRNA and were significantly reduced in those generated by injection of the identical cells expressing PKM2 shRNA, as shown by IHC and western blot analyses." (PMID 33071283, 2021). "Another study found that tumor cells could overexpress PCNA, which can associate with HLA I molecules forming an inhibitory ligand complex." (PMID 32774149, 2020). "Indeed, IGF1R/PCNA colocalization in individual tumors was stronger in areas which are associated with higher proliferation (tumor invasive front) and genomic instability (dysplastic areas and cells with greater nuclear atypia)." (PMID 32701997, 2020). "Previously we reported the identification and characterization of a novel class of small-molecule PCNA inhibitors that bind directly to PCNA trimers, stabilize the trimer structure, reduce PCNA association with chromatin, inhibit DNA replication, and selectively inhibit tumor cell growth." (PMID 31600334, 2019). "Finally, PCNA encodes for a proliferating cell nuclear antigen, which has high expression in tumor tissues." (PMID 31086608, 2019). "Therefore, it is possible that parkin KO reduced p21 ubiquitination and degradation, leading to increased p21/CDK2 or p21/PCNA complex association, which ultimately resulted in the inhibition of tumor growth through cell cycle arrest." (PMID 31112565, 2019). "To understand the underlying mechanism(s) of tumor inhibition by these two polyphenols we analyzed by immunohistochemistry the apoptotic marker, activated caspase-3, and the proliferation marker, PCNA." (PMID 31143704, 2019). "We decided to investigate the function of seven selected target genes (Cycb, os, upd2, upd3, Fancl, PCNA, and dpa) on tumor development by knocking down their expression in the sensitized + Not3-tumor model (independent RNAi constructs/loss-of-function mutants were tested per gene)." (PMID 30144809, 2018). "Western blot analysis on the xenograft tumor tissues further confirmed that the reduced tumorigenicity was associated with the inactivation of GSK3β/mTORC1 signaling and its downstream molecules, and the cellular proliferation marker PCNA." (PMID 30523261, 2018). "Thus, we first analyzed the cellular composition in tumor-associated TLO by staining prostatectomy specimens with antibodies specific for PCNA, CD8, and CD20." (PMID 28567040, 2017). "Indeed, our results demonstrated that orally administered and supplemented drinking water with ETH-UF-LG and HW-WT remarkably reduced tumor growth, decreased PCNA expression, and caused double-stranded DNA breaks in the tumors cells relative to the control." (PMID 29340014, 2017). "In addition, dysregulation of the G1 to S transition is one of the most important reasons for tumor formation, which is tightly linked to unregulated PCNA and Cyclin D1 expression." (PMID 27492854, 2016). "Also, we found tumor cells in the base wells were associated with a higher percentage of Ki67+ cells and an increased PCNA expression." (PMID 26762853, 2016). "High expression of PPARα, high Karnofsky Performance Status (KPS) score, total tumor resection, and high levels of the proliferation markers, Ki-67, PCNA, P170 and high TOPO II were all associated with overall survival, whereas gender and increasing age were not." (PMID 27835866, 2016). "Therefore, overexpression of PCNA in tumor tissue associates with bias towards NKp44-1dominant inhibitory profile." (PMID 27765926, 2016). "Importantly, 4-MD reduced colony formation in soft agar and inhibited tumor growth in mice xenograft model in association with the reduced expression of PCNA, Ki67, p-STAT3, and Survivin." (PMID 26755649, 2016).
tumor (continued). "In contrast in HCC, which is a tumor type associated with compression of surrounding tissue and a total loss of normal tubular architecture, we observed considerable nuclear localization of PCNA but Maid expression was reduced compared to normal liver." (PMID 26107180, 2015). "To assess tumor-associated, growth-independent signals, we adjusted marker levels to remove any association with proliferation and recalculated fup (i.e., accounting for the meta-PCNA signature)." (PMID 26555223, 2015). "In addition, PCNA and Bcl-2 expression have been reported to be closely associated with tumor progression and poor overall survival in PCa." (PMID 26622816, 2015). "Moreover, the anti-tumor effects of TQ were associated with reduced cell proliferation and increased apoptosis by western blot analysis of PCNA and cleaved PARP, respectively." (PMID 26552746, 2015). "Moreover, based an initial SAR analysis, we identified 46 analogs of PCNA-I1 and investigated and compared their effects on PCNA trimer stabilization, tumor cell growth, and chromatin-associated PCNA with PCNA-I1." (PMID 25729582, 2015). "At all DOX doses, the short I2 treatment induced adjuvant antineoplastic effects (decreased tumor size and proliferating cell nuclear antigen level) with significant protection against body weight loss and cardiotoxicity (creatine kinase MB, cardiac lipoperoxidation, and heart damage)." (PMID 23705792, 2013). "IgG expression was associated with tumor differentiation, pTNM stage, lymph node involvement and inflammatory infiltration and positively correlated with the expressions of Cyclin D1, NF-κB and PCNA." (PMID 23133595, 2012). "PCNA is closely linked to tumor biological behaviors and malignancy." (PMID 18366613, 2008). "Previous studies have shown that PCNA is overexpressed in HCC tissues compared to normal liver tissues, and is associated with aggressive tumor behavior, poor differentiation, and unfavorable clinical outcomes, suggesting that PCNA may be a potential target for the treatment of HCC." (PMID 40313621, 2025). "Therefore, a marked increase in PCNA-positive tumor cells may be associated with the presence of more aggressive angiogenesis in the H group." (PMID 37175975, 2023). "Immunohistochemical staining showed that the number of PCNA-positive cells within the tumor tissue was lower than in the model group, thus indicating that the mechanism underlying the inhibitory effect of SBLPE on tumor proliferation may be related to the inhibition of high PCNA expression." (PMID 34257693, 2021). "Furthermore, PCNA expression showed a positive correlation with histological grading, with an increase in PCNA expression being associated with a poorly differentiated tumour and a reduced expression of PCNA suggestive of well-differentiated OSCC." (PMID 31672124, 2019). "Notably, cyclin D1 and PCNA were induced in BRCA1-deficient tumor tissues." (PMID 30652068, 2018). "Importantly, in this group of cancer patients, Ki67 and PCNA (conventional markers of cell proliferation) were associated with tumor progression, as might be expected." (PMID 28978020, 2017). "Furthermore to investigate whether SPAG9 siRNA treated animals which showed reduced tumor growth was associated with reduced cellular proliferation, serial tumor sections were probed for PCNA expression." (PMID 24330581, 2013). "Thus, from this data we cannot say whether PCNA+ TAMs are M1 or M2 cells, but only that they are more associated with an M1-type tumor immune microenvironment." (PMID 24205370, 2013). "Immunohistochemical analysis showed that tumor tissues treated with high doses of VER exhibited reduced levels of PCNA, Bcl-2, vimentin, MMP-2, p-AKT, and p-PI3K compared with the control group." (PMID 41158757, 2026).
tumor (continued). "The IHC analysis of xenograft tumor tissues showed that the overall staining intensity of PCNA, Ki67, and TWIST1 was markedly increased in the SOX11 overexpression group but decreased in the SOX11 knockdown group when compared with the control group." (PMID 41511366, 2026). "Consistent with this enhanced tumor control, immunofluorescence of xenograft tissues showed that PrPC, particularly with 5-FU, reduced intratumoral PrPC and PCNA and decreased CD31-positive microvessels and α-SMA-positive vessel structures." (PMID 41683587, 2026). "In contrast, 89% of the animals in the DMBA-induced group demonstrated a marked increase in tumor burden, characterized by structural disorganization, dense clusters of malignant cells, and elevated PCNA and TNF-α expression levels (p < 0.0001)." (PMID 40430573, 2025). "The patients in the 4q loss group had a larger average tumor size than the patients in the PCNA amp group, and the WT group had the smallest average tumor size (Kruskal–Wallis test, p = 0.029)." (PMID 39762212, 2025). "In vivo experiments also confirmed that repression of the PCNA/PARP1 axis significantly reduced HCC tumor growth." (PMID 40313621, 2025). "Anti-PD-1 therapy reversed these effects, leading to decreased tumor volume and weight, reduced Ki-67 and PCNA expression, and increased CD8+ and IFN-γ+CD8+ T cell infiltration." (PMID 40924302, 2025). "It has been reported that tangeretin inhibits the proliferation of tumor cells by downregulating the PCNA (proliferating cell nuclear antigen), COX-2 (cyclooxygenase), and Ki-67 levels." (PMID 39860170, 2025). "In line with the reduced tumor growth, PCNA-positive cells were significantly decreased in CL7 group." (PMID 41378295, 2025). "TPCS cultured for 4 days maintained an elevated number of PCNA+ tumor cells, an αSMA+ stroma, and maintenance of both CD3+ T cells and F4/80+ macrophages when cultured for 4 days, albeit with a modest reduction in their numbers being observed after 2 days." (PMID 40377490, 2025). "IHC analysis of proliferating cell nuclear antigen (PCNA) revealed that treatment with iRGD-TRP-PK1-RBCVs loaded with Dox or CDDP effectively reduced PCNA expression in tumour tissues." (PMID 39744235, 2025). "Itspecifies that PCNA executes a multifaceted function in cancer developmentand progression, although further investigations are needed to graspthe tumor-specific mechanisms completely." (PMID 40657100, 2025). "Proliferating cell nuclear antigen (PCNA) reflects the status of cell proliferation and is located mostly in the nuclei of normal proliferating cells and tumor cells." (PMID 41024256, 2025). "The apoptotic marker (cleaved caspase 3) and proliferation marker (Ki67 and PCNA) staining ascertained that UBAP2L knockdown enhance the anti-tumor activity of sunitinib in vivo through the inhibition of proliferation and the promotion of apoptosis." (PMID 41029457, 2025). "The genetic variation in PCNA in diverse tumor subtypes from TCGAcohorts was investigated using cBioPortal." (PMID 40657100, 2025). "Among the PCNA-associated hubs, ATM, HDAC1, and MDM2 showed strong correlations with the infiltration of multiple immune cells, highlighting their roles in tumor–immune interactions." (PMID 40430573, 2025). "The results showed that BAY218 reduced the incidence of tumours post Kyn treatment and reduced the expression of PCNA." (PMID 39904603, 2025). "IHC staining of the subcutaneous tumor tissue formed by HCCLM3 cells revealed that TAS4464 treatment significantly reduced PCNA protein expression and the number of Ki-67-positive cells." (PMID 40164590, 2025).
tumor (continued). "IHC staining further showed that PCNA expression and the number of Ki-67-positive cells were reduced in the subcutaneous tumor tissues of the Flag-NUB1 group." (PMID 40164590, 2025). "Immunocytochemical analysis of all DEN treated groups was carried out for tumor markers (collagen IV, PCNA, keratin 18 and E-Cadherin)." (PMID 40475465, 2025). "Western blot analysis of tumor tissues revealed increased E-cadherin expression, decreased vimentin expression, and reduced levels of the PCNA, indicating that G1 can modulate cell phenotype and suppress cell proliferation." (PMID 40867252, 2025). "PCNA can effectively reflect the proliferation activity of cells, to objectively evaluate the proliferation status of tumor cells." (PMID 40607420, 2025). "The presence of PCNA on the tumor cell surface acts as an IC via the inhibitory axis involving NKp44-1 and ITIM, facilitating tumor cell evasion of NK cell-mediated immune clearance." (PMID 40463500, 2025). "Functional experiments confirmed that TRIP13 contributes to ccRCC malignancy by enhancing tumor proliferation (via Ki67 and PCNA), promoting migration and invasion, and facilitating immune escape." (PMID 41487520, 2025). "Tumour growth was further confirmed by histological assessments with H&E staining and PCNA immunohistochemical staining." (PMID 39843398, 2025). "Our results showed an increase in CD-44 positive staining in Nuak2-OE tumors compared to control tumor-bearing mice, while Nuak2-CR tumors had significantly fewer Ki67, PCNA, and CD-44 positive cells." (PMID 40770117, 2025). "Further studies in animal models are needed to validate the effects of targeting PCNA/AR interaction on tumor growth, and cyclin A2 and AR expression in tumor lesions." (PMID 40391771, 2025). "PCNA is aberrantly expressed on the tumor cell surface, where it binds the NKp44 receptor and suppresses natural killer (NK) cell activation, enabling immune escape." (PMID 41170373, 2025). "All the results above indicated that PCNA amplification promoted tumor cell proliferation in intestinal-type patients." (PMID 39762212, 2025). "Like Ki67, a high expression level of PCNA typically implies a high neoplasm recurrence rate and an unfavorable prognosis." (PMID 41132724, 2025). "IHC staining revealed that the CD38‐EVs‐DoxMNs group exhibited the lowest Ki‐67 and PCNA expression compared to all other groups, indicating the most potent tumour proliferation inhibition." (PMID 40317915, 2025). "Results indicated a notable reduction in PCNA and ki67 expressions in tumor tissues after resveratrol treatment." (PMID 40458080, 2025). "Cellular immune indicators were also significantly improved, and both apoptosis and PCNA expression in tumor tissues were improved." (PMID 39897929, 2025). "The IHC results showed that Erianin can further reduce the proportion of Ki67 and PCNA positive cancer cells and increase the content of the tumor apoptosis marker Cleaved Caspase-3." (PMID 40919243, 2025). "In vivo, G1 reduced liver metastasis, increased E-cadherin, and decreased vimentin and proliferating cell nuclear antigen in primary tumor tissues and increased ADAMTS1 at the tumor edge." (PMID 40867252, 2025). "PCNA levels were substantially elevated insignaling pathways in most tumor types, signifying oncogenic synergybetween mechanistic dysregulation and proliferative ability mediatedby PCNA." (PMID 40657100, 2025). "Decreased PCNA staining and increased apoptotic cells were seen in tumor xenografts of cells expressing C1QL1." (PMID 40583061, 2025). "While this strategy increased targeting specificity, the potential for systemic on-target toxicity remained a significant concern due to PCNA’s widespread expression and the difficulty of achieving tumor-specific delivery for peptides." (PMID 41170373, 2025).
tumor (continued). "A monoclonal antibody (mAb) targeting human PCNA, 14-25-9, has been shown to effectively recognize cell surface PCNA on both solid and leukemic cancer cell lines, as well as tumor cells derived from patient-derived xenografts." (PMID 41024300, 2025). "Moreover, as a marker for assessing the proliferative status of cells, PCNA is closely associated with the proliferative activity and DNA damage repair capacity of cancer cells, and its expression level is frequently utilized as an indicator of tumor prognosis." (PMID 41132724, 2025). "We performed RDA analysis to identify associations between the intratumoral microbiota and clinical indicators (including PCNA expression and tumor incidence)." (PMID 41395468, 2025). "Among these, seven genes, namely, RRM2, KIF11, ANLN, CDC20, YWHAZ, DTL, and PCNA, exhibited significantly elevated expression in tumor samples (p ≤ 0.05)." (PMID 41487287, 2025). "The tumor microenvironment strongly influences the efficacy of PCNA inhibitors by regulating drug delivery, immune evasion, and resistance mechanisms." (PMID 41170373, 2025). "PCNA expression(mRNA) was also assessed across tumor cell line types by HPA, which demonstrated low cancer specificity." (PMID 40657100, 2025). "Only 50 μM TMZ treatment significantly reduced the number of PCNA-positive cells in the U87 tumor on the CAM." (PMID 40725030, 2025). "In terms of tumor cell proliferation, quercetin had a significant inhibitory effect on cell proliferation during treatment, as determined by PCNA analysis (SMD -8.22, 95% CI: −10.48 to −5.95, p < 0.00001)." (PMID 40978482, 2025). "According to the immunohistochemical results, the Ki-67 and PCNA levels in the primary tumor tissues were markedly reduced in the 89-treated group, indicating the inhibition of 89 against the tumor cell proliferation in vivo." (PMID 40830098, 2025). "The time-intensity curve(TIC) parameters were extracted and the expression levels of microvessel density(MVD), vascular endothelial growth factor(VEGF), Ki-67 and PCNA in tumor tissues were detected and analyzed." (PMID 40994954, 2025). "Elevated expression of pAKT and PCNA further indicated continuous rapid proliferation of tumor cells." (PMID 41208884, 2025). "Consistently, in comparison to the siControl RNA group, the expression level of the PCNA protein in tumor cells transfected with siSNRPE RNA was markedly decreased." (PMID 40386046, 2025). "The immunohistochemical staining of mammary gland tumor cells has also shown pronounced PCNA activity, supporting its relevance as a marker of tumor progression." (PMID 40430573, 2025). "Immunohistochemical analysis also showed increased expression of the apoptosis marker cleaved-caspase 3 and decreased expression of the proliferation marker PCNA in tumor tissues following combination treatment." (PMID 40347254, 2025). "High Ki‐67 expression correlates with increased tumor aggressiveness and poor survival, while PCNA and PHH3 indicate DNA replication and mitotic activity." (PMID 40051490, 2025). "For instance, phosphorylation of PCNA at tyrosine 211 (Y211) has been shown to promote metastatic dissemination and sustain cancer stemness, highlighting its role in tumor evolution." (PMID 40313621, 2025). "Compared with control group, HQF significantly reduced the expression of Ki67 and PCNA in the subcutaneous tumor tissues (p < 0.01)." (PMID 39972480, 2025). "PCNA in the tumor control evidenced 67 ± 10.1% of cells in the S phase of cell cycle at variable fluorescence intensity as indicative of asynchrony." (PMID 40868059, 2025).